BCS1L (BCS1 ubiquinol-cytochrome c reductase complex chaperone)
Description:
Chaperone necessary for the incorporation of Rieske iron-sulfur protein UQCRFS1 into the mitochondrial respiratory chain complex III. Plays an important role in the maintenance of mitochondrial tubular networks, respiratory chain assembly and formation of the LETM1 complex.
Synonyms: h-BCS1; BCS1; Hs.6719; BCS; h-BCS; BJS; FLNMS; GRACILE; MC3DN1; PTD
Tractability: Antibody: UniProt predicts a signal peptide or a membrane-spanning region. PROTAC: ubiquitination databases record sites on it; its protein half-life has been measured.
Gene: Protein-coding gene on chromosome 2 (218,658,764 to 218,663,466, forward strand). Ensembl gene ENSG00000074582.
Subcellular location: Mitochondrion inner membrane
Subcellular location (Human Protein Atlas): Vesicles; Mid piece
Pathways (Reactome):
Metabolism: Complex III assembly
Protein localization: Mitochondrial protein import
Gene Ontology:
Molecular function: protein binding; ATP hydrolysis activity; ATP binding
Biological process: mitochondrial respiratory chain complex I assembly; mitochondrial respiratory chain complex III assembly; mitochondrial respiratory chain complex IV assembly; mitochondrion organization; protein insertion into mitochondrial inner membrane from matrix
Cellular component: mitochondrial inner membrane; mitochondrion; respiratory chain complex III
Genetic constraint (gnomAD): Loss-of-function variants: 39 observed, 53.17 expected, observed/expected ratio (o/e) 0.73, 90% interval 0.57 to 0.96. The upper end of that interval is the gene's LOEUF score, 0.96, which puts it in group 4 of 6, group 1 being the genes least tolerant of losing a copy. Missense variants: 394 observed, 569.09 expected, observed/expected ratio (o/e) 0.69, 90% interval 0.64 to 0.75. Synonymous variants: 193 observed, 221.21 expected, observed/expected ratio (o/e) 0.87, 90% interval 0.77 to 0.98.
Gene-disease validity (ClinGen):
ClinGen rates the evidence that BCS1L causes each of these diseases.
Bjornstad syndrome (autosomal recessive): Definitive. Bjrnstad syndrome is characterized by congenital sensorineural hearing loss and pili torti.
mitochondrial disease (autosomal recessive): Definitive.
Leigh syndrome (autosomal recessive): Limited. A progressive neurological disease defined by specific neuropathological features associating brainstem and basal ganglia lesions.
Homologues: Orthologues: chimpanzee BCS1L (100% identical), macaque BCS1L (99% identical), dog BCS1L (96% identical), guinea pig BCS1L (96% identical), rabbit BCS1L (95% identical), rat Bcs1l (95% identical), pig BCS1L (94% identical), mouse Bcs1l (94% identical), tropical clawed frog bcs1l (78% identical), zebrafish bcs1l (77% identical), Drosophila melanogaster Bcs1 (61% identical), Caenorhabditis elegans bcs-1 (49% identical).
Diseases named in the same sentence as BCS1L in open-access papers:
BCS1L is named in the same sentence as 47 diseases in open-access papers, as found by Europe PMC text mining. Sharing a sentence is not in itself a finding about the gene and the disease. The quoted sentences say what the papers report.
GRACILE syndrome (14 papers, 2008 to 2025). GRACILE syndrome is an inherited lethal mitochondrial disorder characterized by fetal growth restriction (GR), aminoaciduria (A), cholestasis (C), iron overload (I), lactacidosis (L), and early death (E). "The GRACILE syndrome is caused by a homozygous missense mutation in BCS1L (c.A232G, p.S78G), which encodes a translocase required for the incorporation of RISP into mitochondrial Complex III." (PMID 41149808, 2025). "This is demonstrated by findings that some mutations of BCS1L cause Leigh Syndrome (e.g., P99L), while other mutations in this protein alternatively cause GRACILE syndrome (e.g., S78G)." (PMID 36799301, 2023). "It is important to note that growth retardation, aminoaciduria, cholestasis, iron overload, lactic acidosis, and early death (GRACILE) syndrome is a very severe autosomal recessive human condition linked to one specific BCS1L mutation (p.Ser78Gly)." (PMID 36830747, 2023). "In contrast to other BCS1L pathological variants, liver failure seems to be a determinant component for the early-onset lethality of GRACILE syndrome." (PMID 36830747, 2023). "Diseases caused by BCS1L mutations range from the mild Björnstad syndrome, with brittle hair (pili torti) and sensorineural hearing loss to the fatal GRACILE syndrome." (PMID 28427446, 2017). "To elucidate functions of BCS1L in general, and the pathophysiologic mechanisms in GRACILE syndrome in particular, we introduced the Bcs1l c.232A>G mutation into mice." (PMID 22829922, 2012). "To reveal disease mechanism due to such mutations, we have produced a transgenic mouse model with c.232A>G mutation in Bcs1l, the causative mutation for GRACILE syndrome." (PMID 22829922, 2012). "In man, mutations in BCS1L gene are responsible for pathologies with various clinical presentations e.g. GRACILE syndrome." (PMID 18523582, 2008). "In conclusion, we have discovered and characterized new clinical phenotypes associated with BCS1L variants, including a patient with a BCS1L-related mitochondrial disease with progressive renal failure and a patient with a GRACILE syndrome harbouring a novel BCS1L variant." (PMID 31435670, 2019). "Interestingly, mutation in BCS1L is associated with GRACILE syndrome, a genetic disease characterized by growth and mental retardation." (PMID 31404209, 2019). "In its most severe form, BCS1L deficiency causes GRACILE syndrome." (PMID 28427446, 2017). "In the GRACILE syndrome, the incorporation of Rieske iron-sulfur protein (RISP/UQCRFS1) into the mitochondrial respiratory chain complex III is decreased due to the BCS1L mutation, but the magnitude is highly tissue-specific." (PMID 41149808, 2025). "Although not considered as a main clinical feature in most mitochondrial diseases, iron overload has been reported in GRACILE syndrome, caused by a mutation in the complex III assembly factor BCS1L." (PMID 35663391, 2022). "Over the past 20 years, the BCS1L gene has emerged as the main cause of complex III deficiency, leading to conditions such as GRACILE syndrome, Björnstad syndrome and severe metabolic syndromes." (PMID 34274978, 2021). "Taken together, these observations point out to the possibility that liver-disease might be a specific effect of BCS1L dysfunction only in human GRACILE syndrome." (PMID 34274978, 2021). "Intriguingly, Finnish patients carrying the homozygous missense variants p.(Ser78Gly) in BCS1L presenting with a GRACILE syndrome had no detectable Complex III defect and no neurological findings; however, these patients had increased iron overload." (PMID 31435670, 2019).
Björnstad syndrome (8 papers, 2014 to 2025). "Combined with her clinical presentation, the patient was diagnosed with CIII deficiency and Björnstad syndrome caused by a novel mutation in the BCS1L gene after molecular biological examination." (PMID 33126389, 2020). "We reported the first patient with CIII deficiency and Björnstad syndrome in China and identified 1 novel mutation (C.1061_1062insCTA and P. G354delinsGY) in the BCS1L gene." (PMID 33126389, 2020). "Previous reports have identified five Pakistani patients diagnosed with a Tyr301Asp variant in BCS1L affecting the AAA domain presenting with Björnstad syndrome." (PMID 31435670, 2019). "We report the first case of pathogenic BCS1L variants associated with CIII deficiency and Björnstad syndrome in China." (PMID 33126389, 2020). "Herein, we report the first case of a compound heterozygous mutation in the BCS1L gene associated with CIII deficiency and Björnstad syndrome in a 7-month-old Chinese girl." (PMID 33126389, 2020). "Thus, the possibility of BCS1L‐related disease needs to be considered in phenotypes beyond the classical GRACILE and Björnstad syndromes, and this may improve early clinical recognition of the disease." (PMID 34662929, 2021).
Encephalopathy (8 papers, 2013 to 2024). Encephalopathy is a term that means brain disease, damage, or malfunction. "In a recent review the phenotypes of the more than 20 different BCS1L mutations were categorized in three groups; purely visceral, pure encephalopathy and milder phenotypes." (PMID 28427446, 2017). "However, in GRACILE-like patients, and other patients with BCS1L mutations, encephalopathy, together with tubulopathy and liver disease are common features." (PMID 28427446, 2017). "Defective BCS1L (BCS1-like), the human homolog of the yeast Bcs1, may cause various complex III-related pathologies, such as neonatal proximal tubulopathy, hepatic involvement, and encephalopathy." (PMID 39162512, 2024).
lactic acidosis (7 papers, 2014 to 2023). Metabolic acidosis characterized by the accumulation of lactate in the body. "Here we report a male infant having a novel homozygous BCS1L gene mutation and having a distinct clinical presentation associated with profound multisystem involvement and intolerable lactic acidosis." (PMID 35305621, 2022). "Most reported cases of lactic acidosis due to BCS1L mutations usually have an early-onset and is known to be fatal causing early death." (PMID 35305621, 2022).
hepatopathy (3 papers, 2014 to 2017). "Here, we demonstrate that KD ameliorated hepatopathy in CIII deficient Bcs1l mutant mice at the level of liver histology and liver enzymes, mitochondrial structure and function, and gene expression." (PMID 28424480, 2017). "We fed KD to mice with respiratory chain complex III (CIII) deficiency and progressive hepatopathy due to mutated BCS1L, a CIII assembly factor." (PMID 28424480, 2017). "We used our transgenic mouse model with a homozygous c.232A>G mutation in Bcs1l leading to decreased expression of BCS1L and progressive decrease of Rieske iron-sulfur protein in complex III, resulting in hepatopathy." (PMID 24466228, 2014).
cardiomyopathy (1 paper, 2023). A disease of the heart muscle or myocardium proper. "Three out of the 34 OXPHOS genes that did not demonstrate cardiomyopathy in humans did demonstrate cardiomyopathy in mice (Ndufa13, Bcs1l, Aifm1)." (PMID 37103033, 2023).
chronic kidney disease (1 paper, 2019). Impairment of the renal function secondary to chronic kidney damage persisting for three or more months. "It is likely that P1’s brother, who died before any genetic studies could be undertaken, was also affected with biallelic BCS1L variants, given his similar phenotype of chronic kidney disease, epilepsy and learning difficulties." (PMID 31435670, 2019).
deficiencies (1 paper, 2014). "Neurodegeneration caused by mutations of TTC19 are classified as mitochondrial complex III deficiencies (MC3DNs), including MC3DN1 [MIM:124000], which is associated with compound heterozygous or homozygous mutations of the BCS1L gene." (PMID 24397319, 2014).
developmental delay (1 paper, 2025). "In this work, we identified a homozygous c.38A>G variant in the BCS1L gene (p.Asn13Ser) in a 27-month-old male showing proximal renal tubular acidosis, sensorineural hearing loss, hypopigmented hair, and developmental delay." (PMID 40332224, 2025).
sensorineural deafness (1 paper, 2020). "As with other mitochondrial diseases, there are a range of phenotypes with variants in the BCS1L gene ranging from adults with aminoacidura, seizures, sensorineural deafness, and learning difficulties to infants with early death." (PMID 33426505, 2020).
mitochondrial disease (8 papers, 2016 to 2022). "Of the many types of mitochondrial diseases, mutations affecting BCS1L gene are regarded as chief cause of the defective mitochondrial complex-III, affecting normal mitochondrial functioning, and leading to wide variety of phenotypes." (PMID 35305621, 2022). "Mutations in BCS1L are the most frequent cause of human mitochondrial disease linked to complex III deficiency." (PMID 34274978, 2021). "Increased creatinine is the most common clinical biomarker of renal dysfunction, also found in Toni–Debré–Fanconi syndrome, which is a typical tubulopathy linked to several different mutations in BCS1L in newborn infants and other mitochondrial diseases." (PMID 27809283, 2016). "Here, we describe the generation and characterization of the second metazoan model of BCS1L-related mitochondrial disease." (PMID 34274978, 2021).
cancer (2 papers, 2022). A tumor composed of atypical neoplastic, often pleomorphic cells that invade other tissues. "Regrettably, cancer-related studies of the other few candidate genes, including BCS1L, COQ2, and SLC39A8, are still absent, and we will seriously consider deeper research in our future studies." (PMID 36185199, 2022).
BCS1L also shares sentences with these, for which no sentence is quoted: iron overload (7 papers); Aminoaciduria (6); cholestasis (6); pertussis (4); Fanconi syndrome (2); leukemia (2); ovarian carcinoma (2); alopecia totalis (1); bipolar disorder (1); colon tumor (1); conductive hearing loss (1); depressive disorder (1); Dystonia (1); encephalomyopathy (1); epilepsy (1); genetic disease (1); glycogen storage diseases (1); Growth Retardation (1); hypertrichosis (1); infection (1); Leigh syndrome (1); liver failure (1); liver-disease (1); metabolic syndrome (1); metastatic tumors (1); movement disorder (1); myofibromatosis (1); prostate carcinoma (1); proximal renal tubular acidosis (1); psychosis (1).
A further 5 diseases each share a sentence with BCS1L in 1 paper.